PGM1 (phosphoglucomutase 1)
Diseases named in the same sentence as PGM1 in open-access papers (continued):
Sharing a sentence is not in itself a finding about the gene and the disease.
tumor (continued). "Decreased PGM1 expression obstructed glycogenesis pathway, which leads to the increased flow of glucose into glycolysis, thereby promoting tumor cell proliferation and HCC development." (PMID 30335765, 2018). "This study establishes a tumor-suppressive role of PGM1 by regulating glucose trafficking and uncovers a novel regulatory mechanism of PGM1 expression." (PMID 30335765, 2018). "So, we depleted PGM1 in HepG2 cells and examined the proliferation and tumor growth in these cells, which showed that depletion of PGM1 also greatly promoted the proliferation and tumor growth of HepG2 cells." (PMID 30335765, 2018). "Consistently, FOXJ2 overexpression inhibited the colonies formation, and PGM1 depletion almost completely abrogated such phenotypes of tumor cells." (PMID 30335765, 2018). "Taken together, these results reveal a new role of PGM1 as tumor suppressor to inhibit HCC progression." (PMID 30335765, 2018). "FOXJ2 overexpression inhibited glucose consumption and lactate production in tumor cells, which was reversed by PGM1 depletion." (PMID 30335765, 2018). "At 30 days after implantation, we measured the weights of dissected tumors and found that PGM1 depletion accelerated tumor growth of HCC cells." (PMID 30335765, 2018). "PGM1 overexpression elevated the ratio of G-1-P/G-6-P in tumor cells, while this ratio was reduced by PGM1 depletion." (PMID 30335765, 2018). "The cell proliferation assays showed that 2-DG treatment almost completely abrogated PGM1-depletion–enhanced tumor cell proliferation." (PMID 30335765, 2018). "This study suggests that PGM1 also plays a prosurvival role in tumor cells upon glucose deprivation." (PMID 30335765, 2018). "Taken together, these results demonstrate that FOXJ2-dependent PGM1 up-regulation shunt glycolysis to glycogenesis, thereby decreasing the glycolytic intermediates for tumor cell proliferation and HCC development." (PMID 30335765, 2018). "Our findings uncover a new mechanism that forkhead box protein J2 (FOXJ2)–up-regulated PGM1 expression inhibits tumor cell glycolysis, thereby impairing HCC growth." (PMID 30335765, 2018). "Here, we show that FOXJ2 regulates glucose trafficking between glycolysis and glycogen metabolism by increasing PGM1 expression to inhibit tumor cell glycolysis and proliferation." (PMID 30335765, 2018). "For instance, sc-seq has uncovered malignant cell subclusters enriched in genes associated with histone deacetylase (HDAC) inhibitor response (ATF3, CAV1), inflammation (LXN, PGM1), and hypoxia-linked tumor metastasis (WSB1), highlighting their importance in tumor progression." (PMID 41450739, 2025). "However, PGM-1 can play a tumor-promoting or tumor-suppressing role in an environment-dependent manner." (PMID 39195201, 2024). "Phosphoglucomutase-1 (PGM-1) was found to be a less-abundant protein on the surface of the tumor." (PMID 39195201, 2024). "It has been reported that the infinite proliferation and apoptosis of many tumor cells and cancer cells in the human body are closely related to the PGM1 gene and that PGM1 provides cancer cells with energetic substances, such as glycogen, to support growth, metastasis and invasion of cancer cells." (PMID 38164393, 2023). "All these results suggest that PGM1 might promote or inhibit tumor formation based on the type of tumor and its microenvironment." (PMID 35614441, 2022). "Further, we also found the m6A methylation-related genes FTO, IGF2BP3, and YTHDC1 might participate in the process of PGM1 methylation modification, thereby affecting tumor progression and metastasis." (PMID 35251177, 2022). "The influence of PGM1 was further investigated by studying tumor formation in vivo." (PMID 35614441, 2022). "A mouse tumor model was used to investigate the action of PGM1 in vivo." (PMID 35614441, 2022). "Thus, PGM1 can play a tumor-promoting or anti-tumor-promoting role in an environmentally-dependent manner." (PMID 35614441, 2022).
tumor (continued). "Thus, it appears that PGM1 exerts a tumor suppressive affect by regulating both apoptosis and the S phase of cells." (PMID 35614441, 2022). "Along this line, higher expression of CaIX, Phd3, Slc7a5, Glut1, Pgm1 occurred but not Ndrg1 in a Vhl-deficient renal cell mouse model when compared with non-tumor renal region, which is in line with our data in Vhl-deficient kidneys." (PMID 33321829, 2020). "In contrast, PGM1 overexpression significantly impaired the tumor growth of SK-Hep1 cells." (PMID 30335765, 2018). "We therefore wondered whether PGM1 inhibits tumor growth through regulating this glucose trafficking." (PMID 30335765, 2018). "Among the predicted transcription factors, FOXJ2 was the first transcriptional factor that might regulate PGM1 expression and was also reported to suppress tumor growth." (PMID 30335765, 2018). "PGM1 overexpression greatly inhibited the proliferation and colony formation of tumor cells." (PMID 30335765, 2018). "Importantly, PGM1 may reverse the inhibitory effect of IRF6 on glycolysis-mediated tumor cell proliferation." (PMID 40796729, 2025). "Therefore, we hypothesized that reduced levels of PGM1 might adversely affect energy metabolism, leading to a remodeling of tumor cell physiology with a shift toward the use of aerobic glycolysis." (PMID 35614441, 2022). "In the present study we identified four candidate tumor-associated antigens, including chaperonin containing TCP1 subunit 5 (CCT5), heat shock 70 kDa protein 8 isoform 1 (HSP70), eukaryotic translation elongation factor 1 gamma (eEF1), and phosphoglycerate mutase 1 (PGM1)." (PMID 28969060, 2017). "To determine the value of the PGM1 level as a CRC biomarker, we used the PCR to measure PGM1 mRNA levels in 76 pairs of tumor and matched adjoining normal tissue." (PMID 35614441, 2022). "The translational upregulation of PGM1, UGP2 and GSK3A mediated by MYCT1 and RACK1 adjusted the flux of glycogen synthesis and glycogen shunt, which is crucial for modulating the tumor metabolic reprogramming." (PMID 35281731, 2022). "The expression of differential genes related to PPP, including TKT, TKTL1, PGM1, GPI, FBP2, ALDOA and ALDOC, were all upregulated in WDLPS tumor samples, which were validated by Real-time Quantitative PCR (RT-qPCR)." (PMID 36557266, 2022). "The results showed that HK2, PGM1, PPP1R3C, GYS1, and G6PD were significantly up-regulated in ccRCC tumor tissues." (PMID 34522206, 2021). "For the metabolic alterations, PGM1 expression downregulation suppressed lactate production and facilitated FASN activity in tumor tissues." (PMID 34507580, 2021). "To investigate the role of PGM1 in HCC, we performed immunohistochemistry (IHC) experiments to examine PGM1 expression in 69 pairs of tumor tissues and corresponding peritumoral tissues from HCC patients." (PMID 30335765, 2018). "In the present study, we demonstrate that PGM1 expression in HCC cells inhibits cell proliferation and tumor growth by diverting glucose into glycogen synthesis from glycolysis with sufficient extracellular glucose." (PMID 30335765, 2018). "PGM-1 is essential to address glucose to glycogen synthesis; thus, a reduction in PGM-1 levels in CRC cells could stimulate cellular proliferation and tumor growth by enhancing the glycolytic pathway as previously proposed." (PMID 39195201, 2024). "Genes involved in glycolysis (ALDOA, LDHA, PGK1, PFKL, PGM1) and other metabolic processes (GPX4, PRDX4, ACO2, ASPH, IDH2, SQLE, NPC2, SPTSSA) were upregulated in primary tumor cells, suggesting that the metabolism in primary tumors was distinct from that in their matched metastasis." (PMID 39225101, 2024).
tumor (continued). "Phosphoglucomutase-1, PGm1 (P38652) had higher concentrations again in both leucine groups with or without tumour implant than the C and W groups." (PMID 32668598, 2020). "Growth curves and colony formation assays showed that rescued expression of rPGM1 WT, but not rPGM1 G121R, abrogated PGM1 depletion-increased tumor cell proliferation, colony formation, and tumor growth." (PMID 30335765, 2018). "Similarly, tumor cell-derived TGF-β signaling can trigger the release of several cytokines from CAFs, such as IL-6, CXCL10, and CCL5, which, in turn, drive the upregulation of glycogen metabolism in tumor cells through phosphoglucomutase 1 (PGM1) activation." (PMID 38002286, 2023). "We further overexpressed PGM1 in HepG2 cells and found that the proliferation of HepG2 cells could also be inhibited by PGM1 overexpression, which is similar to SK-Hep1 cells, suggesting that PGM1 is downstream of FOXJ2 and required for FOXJ2-inhibited tumor cell proliferation." (PMID 30335765, 2018). "As shown in S2L and S2M, neither PGM1 overexpression nor PGM1 depletion could affect tumor cell migration and invasion." (PMID 30335765, 2018). "Moreover, PGM1-depletion–promoted tumor growth could not be abrogated by such supplementation either." (PMID 30335765, 2018).
cancer (19 papers, 2012 to 2025). A tumor composed of atypical neoplastic, often pleomorphic cells that invade other tissues. "Here, we demonstrated that the PI3K/AKT pathway is closely linked to PGM1 expression and functions to maintain cancer cell survival and proliferation." (PMID 35614441, 2022). "Both Pgm1 and Tkt (identified here as hub nodes) have been implicated in cancer cell proliferation and have been studied as possible therapeutic targets." (PMID 31285465, 2019). "Cellular metabolism and transportation related genes (ALDOA, SLC16A3, TPI1, LDHB, KCNQ5, and PGM1), which are implicated in human cancer, also remained upregulated even 2-month after radiation exposure." (PMID 23216862, 2012). "PGM1 → securing of the intracellular pool of dNTP →DDR in response to DNA-damaging agents in cancer cells." (PMID 37190033, 2023). "For example, the interaction between CAFs and cancer cells can support glycogenolysis under normoxic conditions and induce phosphorylation and activation of phosphoglucomutase 1, leading to the increased proliferation, invasion, and metastasis of cancer cells." (PMID 35873482, 2022). "PGM1 regulates the glycogenesis process, the dysregulation of which affects glucose catalysis and, consequently, cancer progression." (PMID 34659659, 2021). "Downregulation of PGM1 expression under glucose deprivation enhanced anti-cancer effects of orlistat." (PMID 34507580, 2021). "Recently, the role of PGM1 in cancer has also been widely reported." (PMID 35251177, 2022). "Phosphoglucomutase 1 (PGM1) is known for its involvement in cancer pathogenesis." (PMID 35614441, 2022). "In addition, Ser39, Ser43, and Ser63 of HDAC8 are shown to be phosphorylated by activated AMPK under the condition of glucose deprivation in cancer cells, connecting cancer survival with glycogen pathway via overexpression of phosphoglucomutase 1 (PGM1)." (PMID 35659740, 2022). "To investigate whether PGM1 acts as a cancer suppressor by modulating apoptosis, we evaluated apoptosis via the FCM and TUNEL assays." (PMID 35614441, 2022). "The critical role of PGM1 in regulating glucose metabolism and cancer progression was reported." (PMID 34507580, 2021). "Orlistat could effectively induce cancer cell apoptosis and PGM1 knockdown under glucose deprivation enhanced this anticancer effect in vitro and in vivo by inhibiting the glucose and lipid metabolism." (PMID 34507580, 2021). "In contrast, little is known about the role of PGM1 in cancer." (PMID 30335765, 2018). "In addition, PGM1 expression in cancer cells inhibits cancer cell proliferation." (PMID 38164393, 2023). "This association is important for developing new therapeutic strategies, and indicates that targeting of glycogen metabolism and (or) PGM1 expression may be useful for treating a variety of cancers that show aberrations in these pathways as well as PGM1 expression." (PMID 35614441, 2022). "However, the role played by PGM1 in cancer has remained poorly understood." (PMID 35614441, 2022). "However, the authors did not answer whether HIF-1 and HIF-2 directly regulate PGM1 expression and whether PGM1 expression contributes to cancer progression." (PMID 30335765, 2018). "Therefore, PGM1 may play distinct roles in different cancers." (PMID 35252177, 2022). "However, PGM1 does not show consistent expression patterns in different cancer types, and this might be related to the content of muscle." (PMID 35614441, 2022).
myopathy (7 papers, 2019 to 2023). A disease of the muscle in which the muscle fibers do not function properly. "In conclusion, we established the first in vitro muscle model that enabled us to perform muscle-specific investigation of PGM1-linked myopathy." (PMID 37175952, 2023). "To investigate the pathogenic mechanisms underlying myopathy in PGM1 deficiency, we aimed to generate murine Pgm1 knockout (KO) myoblast lines." (PMID 37175952, 2023). "If confirmed in future studies in human muscle models, this hypothesis would explain the development of myopathy, exercise intolerance, muscle weakness, and other manifestations in PGM1-deficient patients." (PMID 37175952, 2023). "In this study, we established the first in vitro muscle model for PGM1-linked myopathy via genome editing to investigate the muscle-specific role of PGM1 and the effects of D-galactose on myogenic differentiation, nucleotide sugar metabolism, and energy homeostasis." (PMID 37175952, 2023). "The pathogenic mechanisms underlying the development of myopathy and associated muscle defects in PGM1 deficiency remain elusive, and may be related to abnormal protein glycosylation as well as disturbed energy production." (PMID 37175952, 2023).
infection (5 papers, 2017 to 2022). The state of being infected such as from the introduction of a foreign agent such as serum, vaccine, antigenic substance or organism. "As an alternative approach to test for CT295 presence in the host cytoplasm we tested whether infection could restore PGM activity in the cytoplasm of PGM1 deficient fibroblasts." (PMID 35795184, 2022). "Interestingly, unlike ldh1/ldh2 and eno1/eno2 which are expressed in a stage-dependent manner, both PGM isoforms (pgm1 and pgm2) were upregulated 6.4 and 3.1 folds, respectively, in the chronic stage, 28 days post-infection (dpi)." (PMID 35597992, 2022). "Western blot analysis verified three selected proteins involved in glycometabolism pathways, namely PGM1, PKM, and PGK1 were increase over time post the infection." (PMID 35869254, 2022). "The elevated expression of PGM1, PKM, and PGK1 accelerate the glycolysis pathway; thus, we speculated that the B. pseudomallei HNBP001 infection accelerated glucose uptake in host cells." (PMID 35869254, 2022).
metabolic disorder (5 papers, 2015 to 2023). "Deficiency of PGM1 expression during embryonic development can lead to inherited metabolic disorders." (PMID 34507580, 2021). "PGM1 deficiency is an inherited metabolic disorder in humans (CDG syndrome type 1t [CDG1T]), which is also a congenital disorder of protein N-glycosylation." (PMID 30335765, 2018). "FBPase deficiency is often misdiagnosed as several other metabolic disorders, such as G6P deficiency and PGM1 deficiency." (PMID 28420223, 2017). "Recessive mutations in PGM1 (OMIM #171900) cause GSD type XIV or phosphoglucomutase 1 deficiency, a clinically heterogeneous multisystem disorder with features of a metabolic disorder and a congenital disorder of glycosylation." (PMID 25929793, 2015). "Moreover, we presented the first translational application of our tools by performing dynamic isotopic labeling in hiPSCs derived from a patient affected by PGM1 deficiency, a metabolic disorder that affects the synthesis of UDP-glucose and UDP-galactose." (PMID 37443799, 2023). "PGM1 deficiency is an inherited metabolic disorder in humans (CDG1T)." (PMID 30335765, 2018). "Beyond PGM1 deficiency, the customizable formulation of FC-E8 medium is suitable for isotopic labeling not only via glucose but also via fatty acids and some amino acids, offering new opportunities for future applications in other metabolic pathways and metabolic disorders." (PMID 37443799, 2023). "The non-specific clinical features of FBPase deficiency are easily confused with several other metabolic disorders, such as glucose-6-phosphatase (G6P) deficiency and phosphoglucomutase 1 (PGM1) deficiency, especially in the absence of definitive biochemical findings." (PMID 28420223, 2017).
genetic disease (3 papers, 2017 to 2024). "Finally, a better understanding of the human paralogs of PGM1 is timely, given the recent recognition of enzyme deficiencies of PGM1 and PGM3 as the cause of inherited diseases in humans." (PMID 28837627, 2017).
congenital metabolic disorder (2 papers, 2022 to 2023). "PGM1 deficiency is a rare congenital metabolic disorder in which the enzyme responsible for the interconversion of glucose 6-phosohate and glucose 1-phosphate is affected by loss of function." (PMID 37443799, 2023).
bacterial infections (1 paper, 2025). "Phosphoglucomutase-1 (PGM1) expression is upregulated in B cells of patients with PFAPA, which may be due to bacterial infections that lead to sustained B cell activation, requiring enhanced glucose metabolism and glycogen turnover, thereby upregulating PGM1 expression." (PMID 40724870, 2025).
intestinal disorder (1 paper, 2022). A non-neoplastic or neoplastic disorder that affects the small or large intestine. "We describe the case of a 17-year-old girl affected by ASD, reduced growth, neurological development delay, mutations in the PGM1 and EEF1A2 genes (in the absence of clinically manifested disease) and, intestinal disorders such as abdominal pain and diarrhea associated with weight loss." (PMID 35955962, 2022).
PGM1 also shares sentences with these, for which no sentence is quoted: hepatopathy (3 papers); rhabdomyolysis (3); neurological disease (2); autosomal dominant non-syndromic intellectual disability (1); cardiovascular disease (1); colon cancer (1); colorectal adenoma (1); congenital heart disease (1); cutis laxa (1); early-onset epileptic encephalopathy (1); fructose intolerance (1); glycogen storage disease types II (1); goiter (1); Hyperglycemia (1); Hyperinsulinemia (1); Hypertension (1); leukocyte adhesion deficiency (1); malnutrition (1); methylmalonic aciduria type cblA (1); myocarditis (1); oligodendroglioma (1); papillary thyroid carcinoma (1); Parkinson disease (1); periodontitis (1); Protein-losing enteropathy (1); restrictive cardiomyopathy (1); Rosai-Dorfman disease (1); sensorineural hearing loss (1); type 1 diabetes (1).